PHKB (phosphorylase kinase regulatory subunit beta)
Description:
Phosphorylase b kinase catalyzes the phosphorylation of serine in certain substrates, including troponin I. The beta chain acts as a regulatory unit and modulates the activity of the holoenzyme in response to phosphorylation.
Tractability: Small molecule: a structure with a bound ligand is known; a high-quality ligand is known. Antibody: UniProt places it where antibodies can reach, with high confidence; its Gene Ontology location is reachable by antibodies, with medium confidence. PROTAC: ubiquitination databases record sites on it; its protein half-life has been measured; a small molecule that binds it is known.
Target class: Kinase; Protein kinase regulatory subunit; Enzyme
Gene: Protein-coding gene on chromosome 16 (47,461,123 to 47,701,523, forward strand). Ensembl gene ENSG00000102893.
Subcellular location: Cell membrane
Subcellular location (Human Protein Atlas): Golgi apparatus
Pathways (Reactome):
Metabolism: Glycogen breakdown (glycogenolysis)
Gene Ontology:
Molecular function: protein binding; calmodulin binding
Biological process: glycogen catabolic process; generation of precursor metabolites and energy; glycogen metabolic process; carbohydrate metabolic process
Cellular component: phosphorylase kinase complex; cytosol; plasma membrane
Genetic constraint (gnomAD): Loss-of-function variants: 38 observed, 62.91 expected, observed/expected ratio (o/e) 0.6, 90% interval 0.47 to 0.79. The upper end of that interval is the gene's LOEUF score, 0.79, which puts it in group 3 of 6, group 1 being the genes least tolerant of losing a copy. Missense variants: 624 observed, 686.61 expected, observed/expected ratio (o/e) 0.91, 90% interval 0.85 to 0.97. Synonymous variants: 231 observed, 253.33 expected, observed/expected ratio (o/e) 0.91, 90% interval 0.82 to 1.02.
Gene-disease validity (ClinGen):
ClinGen rates the evidence that PHKB causes each of these diseases.
glycogen storage disease IXb (autosomal recessive): Definitive. A disorder of glycogen metabolism caused by a deficiency in liver and muscle phosphorylase kinase subunit b, is autosomal recessive and can lead to hepatomegaly, hypoglycemia after prolonged fasting, and growth retardation.
Homologues: Orthologues: chimpanzee PHKB (99% identical), macaque PHKB (98% identical), pig PHKB (95% identical), mouse Phkb (93% identical), dog PHKB (92% identical), rat Phkb (92% identical), rabbit PHKB (92% identical), guinea pig PHKB (90% identical), tropical clawed frog phkb (81% identical), zebrafish phkb (78% identical), Drosophila melanogaster CG8475 (47% identical), Caenorhabditis elegans Y67D8A.2 (42% identical). Paralogues in human: PHKA2 (37% identical), PHKA1 (36% identical).
Diseases named in the same sentence as PHKB in open-access papers:
PHKB is named in the same sentence as 25 diseases in open-access papers, as found by Europe PMC text mining. Sharing a sentence is not in itself a finding about the gene and the disease. The quoted sentences say what the papers report.
glycogen storage disease (4 papers, 2017 to 2021). "Besides, mutations in PHKB in the liver are associated with glycogen storage diseases." (PMID 31754332, 2019). "Liver phosphorylase b kinase (PhK) deficiency (glycogen storage disease type IX), one of the most common causes of glycogen storage disease, is brought by mutations in the PHKA2, PHKB and PHKG2 genes." (PMID 28410206, 2017). "GSDIX is a group of glycogenoses caused by hepatic phosphorylase kinase deficiency, a hexadecameric enzyme comprising four copies each of four unique subunits encoded by four different genes; PHKA1, PHKA2, PHKB, and PHKG2." (PMID 34946936, 2021).
glycogen storage disease IXb (3 papers, 2014 to 2024). "This case report outlines an exceptionally rare deletion-type mutation in the PHKB gene causing GSD type IXb and presents comprehensive clinical, laboratory, and molecular findings." (PMID 39188489, 2024). "We present a case report of an exceedingly rare deletion-type mutation in the phosphorylase kinase B (PHKB) gene causing GSD type IXb, offering a comprehensive evaluation of clinical, laboratory, and molecular findings." (PMID 39188489, 2024). "This case underscores the rarity and diagnostic challenges associated with GSD type IXb, caused by a rare deletion-type mutation in the PHKB gene." (PMID 39188489, 2024). "PHKB (phosphorylase kinase regulatory subunit beta) is involved in glycogen metabolism and associated with glycogen storage disease IXb, a disease also known as phosphorylase kinase deficiency in liver and muscle." (PMID 36457054, 2022).
liver cirrhosis (2 papers, 2022 to 2024). "More recently, early appearance of liver cirrhosis in a 2 years old child with homozygous mutations in PHKB has been reported." (PMID 35725468, 2022).
adenoma (1 paper, 2024). A neoplasm arising from the epithelium. "Some MP-RNAs (ARID4B, CPT1A, PHKB) had increased number of partners in adenoma samples than in the paracancer samples but decreased in cancer samples." (PMID 38773399, 2024).
colorectal cancer (1 paper, 2019). A primary or metastatic malignant neoplasm that affects the colon or rectum. "Although this observation was inconsistent with the function of PHKB in colorectal cancers, data from clinical patients indicated that PHKB was a potential tumor suppressor in HCC." (PMID 31754332, 2019). "In colorectal cancer, the authors believe that PHKB may promote glycogen degradation, thereby maintaining tumor cell survival." (PMID 31754332, 2019). "The different function of PHKB between colorectal cancer and liver cancer may attributed to tumor heterogeneity, so even the same molecule may play different biological functions." (PMID 31754332, 2019). "In addition, the specific mechanism by which PHKB involves in colorectal cancer and liver cancer is diverse." (PMID 31754332, 2019). "Moreover, high expression levels of PHKB promoted cancer cell survival and showed a poor overall survival in patients with colorectal cancer, which was indirectly related to glycogen metabolism 8-9." (PMID 31754332, 2019).
gastric cancer (1 paper, 2014). A primary or metastatic malignant neoplasm involving the stomach. "In conclusion, we observed high expression levels of KIAA1199 mRNA in clinical gastric cancer tissue and demonstrated that KIAA1199 protein interacted with PHKB and PYGB in TU-KATO III cell lines." (PMID 25051373, 2014).
Hypotonia (1 paper, 2022). Hypotonia is an abnormally low muscle tone (the amount of tension or resistance to movement in a muscle). "Hypotonia and motor delay can be rarely associated to PHKB and PHKG2 mutations." (PMID 35725468, 2022).
liver cancer (1 paper, 2019). An epithelial or non-epithelial malignant neoplasm that arises from the liver. "Here, we identify the expression of PHKB, a molecule that is indirectly involved in the activation of glycogen phosphorylase, decreased in liver cancer cells." (PMID 31754332, 2019). "Our study for the first time showed that PHKB suppressed the growth of liver cancer cell." (PMID 31754332, 2019). "Low PHKB expression could serve as an independent indicator for predicting poor prognosis in HCC and enhanced the proliferation, invasion, and metastasis of liver cancer cells." (PMID 31754332, 2019). "However, in liver cancer, we found that PHKB may be independent of glycogen metabolism, but be related to p-AKT and p-STAT3 signaling pathway." (PMID 31754332, 2019).
pancreatitis (1 paper, 2023). Inflammation of the pancreas. "The novel mutations mapped in LPL, CFTR, CTRC, and PHKB genes show a potential for new finding in pancreatitis and their clinical-genetic importance for diagnostic and pharmaceutics." (PMID 37603299, 2023).
cancer (3 papers, 2014 to 2024). A tumor composed of atypical neoplastic, often pleomorphic cells that invade other tissues. "Masato et.al found that KIAA1199 can interact with PHKB to promote glycogen degradation and further sustain cancer cell survival." (PMID 31754332, 2019). "Previous studies indicated that PHKB promoted biological functions such as cell proliferation by increasing glycogen breakdown in cancer cells." (PMID 31754332, 2019). "Thus, PHKB may be associated with glycogen metabolism and regulate cancer cell growth." (PMID 31754332, 2019).
tumor (3 papers, 2019 to 2024). "Low PHKB expression was closely associated with tumor number (P=0.015), microvascular invasion (P=0.030), and BCLC stage (P=0.019)." (PMID 31754332, 2019). "Consistently, mice injected with cells overexpressing PHKB showed a significant decrease in both tumor volumes and weights, while cells with down-regulated PHKB exhibited an increase in tumor volumes and weights." (PMID 31754332, 2019). "Based on the relationship between PHKB expression and tumor clinicopathological characteristics, we found that the decrease in PHKB expression was closely correlated with aggressive features." (PMID 31754332, 2019). "Emerging evidence suggests that PHKB plays a role in tumor progression." (PMID 31754332, 2019). "Accelerating glycogen metabolism can play a role in suppressing tumors, several enzymes involved in glycogen metabolism exert tumor-suppressive effects, including the glycogen debranching enzyme AGL and the kinase PhK β-subunit (PHKB)." (PMID 36425064, 2022).
myopathy (1 paper, 2023). A disease of the muscle in which the muscle fibers do not function properly. "Phosphorylase b kinase (PHKB) affects the disorder of skeletal muscle glycogen metabolism and is involved in the process of glycogen decomposition, which leads to the occurrence of related myopathy." (PMID 37142996, 2023).
PHKB also shares sentences with these, for which no sentence is quoted: bladder cancer (1 paper); chronic pancreatitis (1); cyst (1); epilepsy (1); hepatic (1); Hepatic fibrosis (1); hepatocellular carcinoma (1); Hypoglycemia (1); invasive carcinoma (1); liver disease (1); McArdle disease (1); myopia (1); Tarui disease (1).